CEP164 (centrosomal protein 164)
Diseases named in the same sentence as CEP164 in open-access papers:
CEP164 is named in the same sentence as 44 diseases in open-access papers, as found by Europe PMC text mining. Sharing a sentence is not in itself a finding about the gene and the disease. The quoted sentences say what the papers report.
ciliopathies (19 papers, 2014 to 2025). "Consistent with previous functional studies, zebrafish experiments have shown that CEP164 deficiency results in ciliopathy phenotypes, including abnormal heart looping." (PMID 41427249, 2025). "Mutations in CEP164 have been associated with severe ciliopathy phenotypes, such as nephronophthisis, occipital encephalocele, and liver fibrosis, and milder phenotypes, like nephronophthisis with Leber congenital amaurosis." (PMID 39337513, 2024). "Here we describe a patient with an atypical motile ciliopathy phenotype and biallelic CEP164 variants." (PMID 36273371, 2023). "Our patient with mutations in CEP164 was previously found in a cohort analysis of bronchiectasis patients, whereby monogenic ciliopathy gene variants were found in 12% of the cohort." (PMID 36273371, 2023). "In conclusion, variants in CEP164 now need to be correlated with both primary ciliopathy and motile ciliopathy phenotypes." (PMID 36273371, 2023). "The findings from our patient suggest that pathogenic variants in CEP164 can cause both primary and motile ciliopathies, correlating with known CEP164 expression patterns in the human and mouse." (PMID 36273371, 2023). "Homozygous truncations of CEP164 are associated with severe ciliopathy whereas missense mutations generate milder forms of nephronophthisis (NPHP)." (PMID 36074756, 2022). "We propose that, in ciliopathies caused by CEP164 missense mutations (e.g., X1460WextX57 associated with Leber congenital amaurosis or LCA), impairment of IFT provides a mechanism for ciliary dysfunction and disease." (PMID 36074756, 2022). "Mutations in centriole components such as CEP164 that impair cilia formation or function are either incompatible with human life or result in disorders referred to as ciliopathies." (PMID 34499853, 2022). "Homozygous truncations of CEP164 are associated with severe ciliopathy whereas missense mutations generate milder forms of NPHP." (PMID 36074756, 2022). "CEP290 mutations have not been directly related to cell cycle defects, although a related ciliopathy gene CEP164 (alias NPHP15) regulates cell cycle progression and is implicated in DNA damage response signaling." (PMID 28973549, 2017). "More recently, homozygous recessive mutations in CEP164 were shown to be causal for a subset of nephronophthisis-related ciliopathies, with mutant zebrafish models exhibiting both ciliopathy phenotypes and inefficient responses to DNA damage." (PMID 27335639, 2016). "It is intriguing that the same study identifying CEP164 mutations as causative for a subset of nephronophthisis-related ciliopathies also identified causative mutations in MRE11." (PMID 27335639, 2016). "This work provides further evidence that CEP164 mutations can contribute to both primary and motile ciliopathy syndromes, supporting their functional and clinical overlap, and informs the investigation and management of CEP164 ciliopathy patients." (PMID 36273371, 2023). "Thus, our data confirm the genetic data in patients and suggest that two CEP164 mutations that give rise to ciliopathies with comparable strength in patients show differential impacts on ciliogenesis in tissue culture cells." (PMID 34499853, 2022). "The mutations Q11P and R93W in CEP164 are associated with ciliopathies." (PMID 34499853, 2022). "A structural understanding of how ciliopathy mutations affect CEP164 function might therefore inform translational research approaches aimed at alleviating disease progression in patients." (PMID 34499853, 2022). "We hypothesize that Patient 1 presented with severe ciliopathy‐spectrum disease because her nonsense and frameshift CEP164 variants more significantly impair CEP164 function." (PMID 34132027, 2021). "Notably, wdpcp and cep164 are both implicated in human ciliopathies." (PMID 24424412, 2014).
ciliopathies (continued). "Together, our data deepen our understanding of a crucial step in cilia formation and will inform future studies aimed at restoring CEP164 functionality in a debilitating human ciliopathy." (PMID 34499853, 2022). "Mice with germline knockouts of CEP164 present defects in BB docking to cell membranes, thereby generating syndromic ciliopathies." (PMID 35698136, 2022). "We demonstrated that CEP164 (also known as NPHP15), which is mutated in human ciliopathies including nephronophthisis and BBS23,24, directly interacts with and recruits Cby1 to the distal appendages during ciliogenesis." (PMID 34446743, 2021). "Mutations in three genes encoding DAP proteins, namely, CEP83, CEP164, and SCLT1, have been reported to be linked to heritable ciliopathies, such as NPHP and Joubert syndromes." (PMID 34830133, 2021). "In nephronophthisis-related ciliopathies, which are degenerative recessive diseases, mutations of either ZNF423 and Centrosomal Protein 164 (CEP164) or meiotic recombination 11 (MRE11) resulted in alteration of DNA damage pathways." (PMID 29867779, 2018). "Further, a recent study also showed that mutations in MRE11, ZNF423 and CEP164, genes which encode proteins that function within the DDR, can cause nephronophthisis, providing another link between DDR signalling and ciliopathies." (PMID 26908596, 2016). "Here we examine the functional role of CEP164 in nephronophthisis-related ciliopathies and concomitant fibrosis." (PMID 25340510, 2014). "The second CEP164 variant identified in this patient (NM_014956.5 c.4228C > T; Q1410*), was a stop gain in the penultimate exon, not been described previously in CEP164‐ciliopathy patients, with an allele frequency in gnomAD of 0.0008." (PMID 36273371, 2023). "We further showed that CEP164, which is mutated in nephronophthisis and Bardet-Biedl syndrome (BBS), both of which are classified as ciliopathies, directly interacts with and recruits Cby1 to the distal appendage/transition fiber of the mother centriole/basal body during primary ciliogenesis." (PMID 29244804, 2017). "Furthermore, it is unclear what potential strategies could be used to address CEP164 dysfunction in these ciliopathies." (PMID 34499853, 2022). "We describe a female with hypothalamic hamartoma, urogenital sinus, polysyndactyly, and multiple lingual hamartomas consistent with OFDVI with biallelic pathogenic variants in CEP164, a gene associated with ciliopathy‐spectrum disease, but never before with OFDS." (PMID 34132027, 2021). "Finally, our CEP164 conditional KO mouse model will provide a basis for future investigations into the molecular mechanisms of primary and multiciliogenesis in vivo as well as the pathogenesis and mechanisms of ciliopathies." (PMID 29244804, 2017). "To establish the importance of the interface residues Q11, Y73, and S82 in the CEP164-NTD, we purified recombinant CEP1641−109, the ciliopathy mutant Q11P, and the S82A and Y73A mutants." (PMID 34499853, 2022). "CEP164 is expressed in tissues affected in CEP164-NPHP-RC patients, however clinical heterogeneity, commonly seen in ciliopathies, requires further investigation." (PMID 31990917, 2020).
nephronophthisis (10 papers, 2014 to 2024). Progressive tubulointerstitial injury, inherited in an autosomal recessive pattern, caused by mutations in genes involved in ciliary function, which may result in an end stage renal failure. "Human CEP164 mutations are typically described in patients with nephronophthisis‐related primary ciliopathies but have also been implicated in motile ciliary dysfunction." (PMID 36273371, 2023). "The two missense mutations Q11P (homozygous) and R93W (compound heterozygous with a Q525X truncation mutation) in CEP164 are associated with nephronophthisis, while a homozygous CEP164 R93W mutation also has been identified in a patient with BBS (Bardet-Biedl syndrome)-like syndrome." (PMID 34499853, 2022). "Largely identified in nephronophthisis, mutations within DDR genes such as ZNF423, CEP164, NME3, and AATF are sufficient to cause disease via ciliary dysfunction." (PMID 32351541, 2020). "In contrast to Q11P, the other CEP164-NTD-linked nephronophthisis-associated mutation R93W is not located near the TTBK2-CEP164 interface." (PMID 34499853, 2022).
Hydrocephalus (5 papers, 2017 to 2022). Hydrocephalus is an active distension of the ventricular system of the brain resulting from inadequate passage of CSF from its point of production within the cerebral ventricles to its point of absorption into the systemic circulation. "In a conditional knockout mouse model that lacks CEP164 in multiciliated tissues and testes, a profound loss of airway, ependymal, and oviduct multicilia resulted, and the mutant mouse developed hydrocephalus and male infertility." (PMID 36074756, 2022). "Morpholino‐mediated cep164 knockdown in zebrafish disrupts the DNA damage pathway and causes nephronophthisis‐spectrum disease and hydrocephalus." (PMID 34132027, 2021). "We demonstrated that CEP164 removal in these tissues results in a profound loss of multicilia in the airway, ependymal, and oviduct epithelia as well as development of hydrocephalus and male infertility." (PMID 29244804, 2017). "Knockdown of CEP164 in zebrafish resulted in syndromic ciliopathy with ventral body axis curvature, cell death, abnormal heart looping, pronephric tubule cysts, hydrocephalus, and retinal dysplasia." (PMID 36074756, 2022). "We used the MCC-specific CEP164 knockout (FOXJ1-Cre; CEP164fl/fl) and p73 knock-out (p73−/−) mouse models, both of which exhibit a significant loss of multicilia in the ependyma of the cerebral ventricles and communicating hydrocephalus." (PMID 35248089, 2022). "Previous studies have established a ciliogenesis role for CEP164 in the motile cilium and demonstrated CSF defects including hydrocephalus in zebrafish and murine models lacking functional CEP164." (PMID 31990917, 2020).
Joubert syndrome (5 papers, 2018 to 2022). Joubert syndrome (JS) is characterized by congenital malformation of the brainstem and agenesis or hypoplasia of the cerebellar vermis leading to an abnormal respiratory pattern, nystagmus, hypotonia, ataxia, and delay in achieving motor milestones. "Furthermore, we reveal that some Joubert syndrome mutations perturb INPP5E ciliary targeting, and clarify how each CLS works: (i) CLS4 recruits PDE6D, RPGR and ARL13B, (ii) CLS2-CLS3 regulate association to TULP3, ARL13B, and CEP164, and (iii) CLS1 and CLS4 cooperate in ATG16L1 binding." (PMID 36063381, 2022). "In contrast, the Joubert syndrome cluster contained five hits found under starved conditions, CPLANE1, UNC119, PIBF1, and CEP164." (PMID 34685691, 2021). "Some CEP164 NPHP-RC patients show neurological phenotypes, including abnormal developmental delay, intellectual disability and in one patient, cerebellar vermis aplasia, an archetypal feature of Joubert syndrome." (PMID 31990917, 2020).
retinal degeneration (5 papers, 2016 to 2023). Degeneration of the retina. "This provides a potential mechanism for the later onset of retinal degeneration in patients with hypomorphic CEP164 mutations." (PMID 36074756, 2022). "Mutations both in CEP164 and Kizuna are associated with retinal degeneration and dystrophy, suggesting that these two components may play a common role in disease pathogenesis." (PMID 37852252, 2023). "A major finding is that IFT88, IFT57 and IFT140 are depleted gradually after deletion of CEP164 at P16-P21, implicating IFT malfunction as the cause of retina degeneration in rodCep164-/- mice." (PMID 36074756, 2022).
Bardet-Biedl syndrome (3 papers, 2017 to 2022). A ciliopathy with multisystem involvement. "Biallelic CEP164 variants have been identified in multiple individuals affected by ciliopathy‐spectrum disease, including Leber congenital amaurosis, Bardet‐Biedl syndrome, and JS with associated features including obesity, bronchiectasis, liver fibrosis, and intellectual disability." (PMID 34132027, 2021).
holoprosencephaly (3 papers, 2017 to 2022). Holoprosencephaly (HPE) is a complex brain malformation resulting from incomplete cleavage of the prosencephalon, occurring between the 18th and 28th day of gestation, and affecting both the forebrain and face, which results in neurological manifestations and facial anomalies of variable severity. "The Cep164 KO-first mouse allele displayed holoprosencephaly, cardiac looping defects, and edema with lethality at E10.5." (PMID 36407107, 2022). "CEP164-KO embryos exhibit holoprosencephaly, an edematous cardiac sac, heart looping defects, and a truncated posterior trunk at E9.5–10.5, leading to embryonic lethality." (PMID 29244804, 2017). "At embryonic day (E) 7.5, CEP164-KO embryos showed no obvious morphological abnormalities; however, at E9.5 and E10.5, they exhibited holoprosencephaly, cardiac looping defects, an edematous pericardial sac, and a truncated posterior trunk." (PMID 29244804, 2017).
Leber congenital amaurosis (3 papers, 2021 to 2024). Leber congenital amaurosis (LCA) is a retinal dystrophy defined by blindness and responses to electrophysiological stimulation (Ganzfeld electroretinogram (ERG)) below threshold, associated with severe visual impairment within the first year of life. "CEP164(X1460WextX57), identified in a child with Leber congenital amaurosis (LCA), causes a read-through of the stop-codon X1460, adding 57 foreign amino acid residues to the CEP164 C-terminus." (PMID 36074756, 2022).
bronchiectasis (2 papers, 2021 to 2023). Segmental, irreversible dilation of the bronchial tree resulting in the accumulation of secretions which leads to obstruction. "Filtering for biallelic or compound heterozygous CEP164 variants in the rare disease cohort, we identified an adult patient recruited under “non‐CF bronchiectasis” in whom we identified compound heterozygous stop gain variants in CEP164." (PMID 36273371, 2023). "Here we describe a patient with bronchiectasis in whom we identified biallelic CEP164 mutations as the likely cause of an atypical motile ciliary phenotype." (PMID 36273371, 2023).
Infertility (2 papers, 2021 to 2024). "The distal appendage protein CEP164 also plays a role in ED multiciliogenesis, in which mice lacking CEP164 displayed absence of MCCs in the EDs, leading to sperm agglutination and aggregation and ED obstruction, leading to infertility." (PMID 39513856, 2024).
male infertility (2 papers, 2017 to 2021). The inability of the male to effect fertilization of an ovum after a specified period of unprotected intercourse. "In the mouse, Cep164 is highly expressed in spermatids and a conditional knockdown results in male infertility indicating that transition fibre proteins may also act together in sperm cilia as they do in other types of cilia." (PMID 34357392, 2021).
brain aneurysm (1 paper, 2023). A congenital or acquired aneurysm within the cranium. "Brain aneurysm was observed in eight patients (16%), and the causative genes were PKD1 (missense (n = 2), nonsense (n = 1)), PKD2 (missense (n = 1), splice-site (n = 1)), ZNF423 (missense), GLIS2 (missense) or PKHD1 (missense) or WDR19 (splice-site), and CEP164 (missense)." (PMID 36833371, 2023).
frontotemporal dementia (1 paper, 2021). Frontotemporal dementia (FTD) comprises a group of neurodegenerative disorders, characterized by progressive changes in behavior, executive dysfunction and language impairment, as a result of degeneration of the medial prefrontal and frontoinsular cortices. "CEP164 binds to TTBK2, a kinase that phosphorylates tau and contributes to neurodegeneration in frontotemporal dementia." (PMID 33861770, 2021).
glaucoma (1 paper, 2024). Increased pressure in the eyeball due to obstruction of the outflow of aqueous humor. "We selected CEP164 for this experiment because of its known localization to centrosomes and a previously reported observation of myocilin, another known glaucoma-related gene in the centrosomes." (PMID 39337513, 2024).
microcephaly (1 paper, 2014). A congenital or acquired developmental disorder in which the circumference of the head is smaller than normal for the person's age and sex. "cep164 knockdown caused microcephaly, shortened body axis, axis curvature and edema compared to wildtype zebrafish after control injection and in general recapitulates the results of the other published MO." (PMID 25340510, 2014).
nephronophthisis 15 (1 paper, 2016). Any nephronophthisis in which the cause of the disease is a mutation in the CEP164 gene. "Mutations in this gene were previously associated with nephronophthisis 15, thus the current results expand the CEP164-associated phenotypic spectrum." (PMID 27708425, 2016).
Nephropathy (1 paper, 2023). A nonspecific term referring to disease or damage of the kidneys. "Eight heterozygous variants were identified in nephropathy-associated genes (CLCN2, C5orf42, GSN, LMX1B, CEP164, PKD1, ITGB4, and KANK2), but each could be discounted having been inherited from an unaffected parent." (PMID 37148394, 2023).
osteosarcoma (1 paper, 2025). A usually aggressive malignant bone-forming mesenchymal neoplasm, predominantly affecting adolescents and young adults. "In non-ciliated human osteosarcoma U2OS cells, GFP-CCDC92 displayed a ring-shaped distribution at the distal end of the mother centriole, where it colocalized with CEP164." (PMID 41378450, 2025).
pancreatic cancer (1 paper, 2020). "We focused on CEP164 among many ciliary genes because low expression of CEP164 is associated with poor prognosis of pancreatic cancer patients." (PMID 33251215, 2020). "The fact that low CEP164 expression is a poor prognostic factor in pancreatic cancer patients supports this hypothesis." (PMID 33251215, 2020).
renal fibrosis (1 paper, 2025). A final common manifestation of a wide variety of chronic kidney diseases characterized by glomerulosclerosis and tubulointerstitial fibrosis. "Interestingly, loss of CEP164/NPHP15, which shows a similar pattern at the ciliary base, was reported to increase epithelial to mesenchymal transition, a hallmark of renal fibrosis." (PMID 40814602, 2025).
rhabdomyosarcoma (1 paper, 2020). A rare aggressive malignant mesenchymal neoplasm arising from skeletal muscle. "CEP164 is overexpressed in various cancer types, often associated with poor prognosis, and a recent study in rhabdomyosarcoma cells suggested a central role of this gene in proliferation in response to cellular stress." (PMID 32432034, 2020).
cancer (3 papers, 2017 to 2025). A tumor composed of atypical neoplastic, often pleomorphic cells that invade other tissues. "The control genes CEP164, PHACTR4 and MLL3 displayed as expected high mutation frequencies, ranging from 30% to 80% in the MSI cancer cell lines." (PMID 27907910, 2017).
CEP164 also shares sentences with these, for which no sentence is quoted: Meckel-Gruber syndrome (3 papers); Intellectual disability (2); liver fibrosis (2); communicating hydrocephalus (1); cyst (1); developmental delay (1); frontometaphyseal dysplasia (1); hepatoblastoma (1); hypothalamic hamartoma (1); lingual hamartomas (1); lung disease (1); Meckel syndrome type 13 (1); Meckel syndrome, type 2 (1); Obesity (1); occipital encephalocele (1); osteofibrous dysplasia (1); polydactyly (1); Polysyndactyly (1); retinopathy (1); spondylometaphyseal dysplasia (1); tumor (1); ZIKV infection (1).